TRIM73 (tripartite motif containing 73)
Synonyms: TRIM50B
Tractability: No criterion of Open Targets' tractability assessment is met for any kind of drug.
Gene: Protein-coding gene on chromosome 7 (75,395,063 to 75,410,996, forward strand). Ensembl gene ENSG00000178809.
Subcellular location (Human Protein Atlas): Cytosol
Gene Ontology:
Molecular function: ubiquitin protein ligase activity; zinc ion binding
Biological process: innate immune response
Cellular component: cytoplasm
Genetic constraint (gnomAD): Loss-of-function variants: 0 observed, 6.66 expected, observed/expected ratio (o/e) 0, 90% interval 0 to 0.45. That is too few expected variants to judge how well the gene tolerates losing a copy. Missense variants: 14 observed, 104.69 expected, observed/expected ratio (o/e) 0.13, 90% interval 0.087 to 0.21. Synonymous variants: 8 observed, 40.58 expected, observed/expected ratio (o/e) 0.2, 90% interval 0.12 to 0.36.
Homologues: Paralogues in human: TRIM74 (99% identical), TRIM50 (93% identical), MID1 (26% identical), MID2 (26% identical), TRIM27 (26% identical), TRIM72 (24% identical), TRIM11 (23% identical), TRIM68 (23% identical), TRIM22 (23% identical), TRIM39 (23% identical), TRIM4 (22% identical), TRIM41 (22% identical), and 68 more.
Diseases named in the same sentence as TRIM73 in open-access papers:
TRIM73 is named in the same sentence as 7 diseases in open-access papers, as found by Europe PMC text mining. Sharing a sentence is not in itself a finding about the gene and the disease. The quoted sentences say what the papers report.
pancreatic cancer (2 papers, 2020 to 2022). "It suggested that the eight markers: MAPT, SIX3, MIR663, EPB41L3, FAM150A, TRIM73, LOC100128977, and LOC100130148 may serve as potential biomarkers for the early diagnosis of pancreatic cancer." (PMID 33424927, 2020). "However, the multivariate Cox regression analysis indicated that TRIM73, FAM150A, EPB41L3, SIX3, MAPT, LOC100128977, and LOC100130148 might not be independent factors for the prognosis of pancreatic cancer patients." (PMID 33424927, 2020).
breast carcinoma (1 paper, 2022). "Therefore, it is crucial to further explore the specific mechanisms and clinical values of TRIM73 gene mutation in lung adenocarcinoma patients with previous breast cancer." (PMID 35668376, 2022). "Furthermore, the mutations of TRIM73, DLX6 and CNGB1 and high expression of FGF10 and VEGFA might play an important role in the development of lung adenocarcinoma in breast cancer patients." (PMID 35668376, 2022). "Thus, TRIM73, DLX6 and CNGB1 may be relatively characteristic genes in pulmonary adenocarcinoma patients with previous breast cancer." (PMID 35668376, 2022).
colon cancer (1 paper, 2024). "Five TRIM expression was significantly upregulated (TRIM14, TRIM15, TRIM24, TRIM29, and TRIM31), and the other five TRIM genes showed decreased expression (TRIM1, TRIM3, TRIM9, TRIM22, and TRIM73) in both colon cancer (COAD) and rectal cancer (READ)." (PMID 38769340, 2024).
Williams-Beuren syndrome (1 paper, 2011). "Unequal crossing-over and aberrant homologous recombination between the tandem segments that contain TRIM50, TRIM73, and TRIM74 causes Williams-Beuren syndrome in 1/7,500 to 1/25,000 newborns." (PMID 22144910, 2011).
TRIM73 also shares sentences with these, for which no sentence is quoted: lung adenocarcinoma (1 paper); pancreatic adenocarcinoma (1); rectal cancer (1).